WEE1 (WEE1 G2 checkpoint kinase)
Diseases named in the same sentence as WEE1 in open-access papers (continued):
Sharing a sentence is not in itself a finding about the gene and the disease.
cancer (continued). "Adavosertib (AZD1775) is a first-in-class WEE1 inhibitor, currently under investigation in a late-phase trial in different cancer types." (PMID 34440249, 2021). "Both CRISPR and MK‐1775 WEE1 inhibitor analyses suggest that a proper balance of WEE1 inhibition is necessary to achieve cancer‐specific lethality in TNBC cell lines." (PMID 34227743, 2021). "WEE1 plays a significant role in G2/M cell cycle checkpoint arrest, and the occurrence of G2/M phase arrest is conducive to DNA repair of cancer cells." (PMID 34194536, 2021). "Given that single‐agent therapy is believed to be almost equally toxic to normal and cancer cells, the antitumor activity of WEE1 inhibitors monotherapy potentially arises from the increased replication stress in cancer cells." (PMID 34977872, 2021). "The lower Wee1 expression in malignant tumors compared to benign ones suggests that it acts as a tumor suppressor." (PMID 34639030, 2021). "Adavosertib is a first-in-class Wee1 inhibitor that has demonstrated activity against certain cancers." (PMID 34298699, 2021). "A cell viability assessment with a kinase siRNA library in different cancer cell lines demonstrated that Wee1 gene expression correlated with the Wee1 gene copy number, potentially identifying a cause of increased expression." (PMID 34639030, 2021). "Disruption of WEE1 has been investigated in various cancers, and various inhibitors have been used as a treatment through WEE1 regulation, which has yielded good results." (PMID 34646884, 2021). "The available literature highlights a common mechanism of action of WEE1/PKMYT1 inhibitors in cancer cells either in single agent or in combination with DNA damaging agents (chemotherapy/radiotherapy)." (PMID 32958072, 2020). "The identification of molecular vulnerabilities in cancer patients will be fundamental to design novel therapeutic regimens using WEE1/PKMYT1 inhibitors in a chemo/radiotherapy-free, synthetic lethality-based approach." (PMID 32958072, 2020). "PD0166285, another reported WEE1 inhibitor, is a major drug for inducing radiotherapy sensitivity because it can lead cancer cells to fail to perform an IR-induced DDR398." (PMID 32355263, 2020). "Our simulations showed a general increase in Wee1 and a decrease in Myc levels, which would explain an overall less proliferation of cancer cells inside the zebrafish." (PMID 32244760, 2020). "Our data show that SETD8C302R cancer cells are more sensitive to WEE1 inhibition compared with SETD8WT cells, which present a promising therapeutic approach for cancer patients carrying this mutation." (PMID 33042742, 2020). "G2/M checkpoint abrogation through WEE1 inhibition was originally conceived as a strategy to selectively sensitize cancer cells to DNA damaging agents, given that most human cancers rely on the G2/M checkpoint to detect and repair damaged DNA." (PMID 33020398, 2020). "Overall, the data suggest that WEE1/PKMYT1 inhibition is a suitable pharmacological target for combination strategies in cancer." (PMID 32958072, 2020). "Experimental evidence has demonstrated that Wee1 inhibitor AZD1775 significantly inhibits cancer growth and impairs RAD51 focus formation in response to radiotherapy." (PMID 32355263, 2020). "An independent screen of 91 anti-cancer compounds highlighted several drugs targeting the DNA repair pathway as top hits in MCF10A KRAS G12D cells grown in minimal media including WEE1, CHK1/2 and PARP inhibitors." (PMID 32398776, 2020).
cancer (continued). "Among the drugs targeting the DDR pathway, AZD1775 (MK-1775, adavosertib), an inhibitor of the tyrosine kinase WEE1, has shown efficacy in sensitizing many cancer types to DNA damaging agents in both preclinical studies and phase I/II clinical trials." (PMID 33020398, 2020). "As the cancer cells are reliant on disruptionof the apoptosis process, it is thought that the G2 checkpoint isvital for their survival, thereby presenting WEE1 as a promising targetfor cancer therapy." (PMID 33135887, 2020). "WEE1 is a cell cycle and DNA damage response kinase that is emerging as a therapeutic target for cancer." (PMID 32195191, 2020). "WEE1 inhibitors are known to induce abortive mitosis (endomitosis) since cancer cells have polypoid nuclei after WEE inhibition." (PMID 32957652, 2020). "For example, the dependence of many cancer cells specifically on the G2/M checkpoint has led to the development of agents that target this checkpoint, particularly Chk1, Wee1, ATM, and ATR." (PMID 32117972, 2020). "Increasing evidence has indicated that synthetic lethality using ATR, CHK1, or Wee1 inhibitors can be used to exploit oncogene-induced RS in cancer." (PMID 31362335, 2019). "In the present study, a cell viability test using multiple cancer cell lines showed that 92.1 and OCM1 UVM cells were very susceptible to a WEE1 inhibitor (MK-1775) at a clinically tolerable dose." (PMID 31848373, 2019). "AZD1775, an orally available Wee1 inhibitor, has entered clinical trials for cancer treatment following this strategy, with promising results." (PMID 31200459, 2019). "AZD1775, an orally available Wee1 inhibitor, was developed for these purposes and is currently being tested in cancer patients, alone or in combination therapies." (PMID 31200459, 2019). "Induction of DNA damage has been reported as a primary cytotoxic consequence of Wee1 inhibitor in cancers." (PMID 29977914, 2018). "High expression of WEE1 has been reported in some cancers in response to elevated replication stress, and has been associated with tumor progression and poor outcome." (PMID 29448954, 2018). "WEE1 is highly expressed in several cancer types, including hepatocellular carcinoma, cervical cancers, lung cancers, squamous cell carcinoma, colorectal cancers, gastric cancers, leukemia, melanoma, and ovarian cancers." (PMID 29448954, 2018). "Wee1, like many other kinases, has been described as a potential target for cancer therapy, given its deregulation in tumors." (PMID 29343688, 2018). "Having been reported to be overexpressed and predicting poor prognosis in several cancer types (including GC), Wee1 is considered to be a novel therapeutic target against GC." (PMID 29977914, 2018). "AZD1775, a most common selective and potent Wee1 inhibitor, has been reported to synergize with various genotoxic drugs in the treatment of cancers." (PMID 29977914, 2018). "MK-1775, a first-in-class small-molecule inhibitor of WEE1 with undergoing clinical evaluation, abated phosphorylation of CDK1 at Tyr15 and caused mitotic catastrophe in cancer cells." (PMID 30323762, 2018). "Apart from cellular growth inhibition, Wee1 blockade has also been reported to suppress cancer progression, and high expression of Wee1 is identified as a predictor of poor long-term prognosis that often results from metastasis." (PMID 29977914, 2018). "The tyrosine kinase WEE1 is highly expressed in many cancer types and plays a role in cell cycle progression via the G2 checkpoint." (PMID 29882812, 2018). "In this study, we discovered the previously uncharacterised link between the Hippo pathway effector YAP and the sensitivity of cancer cells to a WEE1 kinase inhibitor." (PMID 29928579, 2018). "Wee1 mRNA expression across different cancer types from the Cancer Cell Line Encyclopedia (CCLE) database." (PMID 30068368, 2018).
cancer (continued). "This study provides an explanation behind the previously reported synergy between Wee1- and Chk1- inhibitors observed in preclinical cancer treatment studies." (PMID 28030798, 2017). "Inhibitors of Wee1 kinase are currently in clinical trials for cancer treatment as single agents and in combination with radiation or chemo-therapy." (PMID 28030798, 2017). "WEE1 inhibition sensitizes TNBCs and cisplatin resistant cancer cells to cisplatin-induced lethality, because it not only impairs DNA replication checkpoint more profoundly than inhibition of ATR or CHK1, but also defects G2-M cell cycle checkpoint." (PMID 28262781, 2017). "High Wee1 activity helps reinforce the DNA damage checkpoints and facilitates DNA repair, which in turn allows cancer cells to resist genotoxic therapies." (PMID 29088738, 2017). "Initial pre-clinical studies reported that WEE1 inhibition in combination with DNA damaging agents forced cancer cells into premature mitosis with lethal unrepaired DNA damage resulting in cell death." (PMID 28178688, 2017). "Combined, these data demonstrate that WEE1 mediated H2B Y37-phosphorylation is a recurrent pro-proliferative epigenetic modification in multiple proliferating cancer cells that can be specifically targeted with the WEE1 inhibitor, AZD1775." (PMID 29290954, 2017). "Overexpression of Wee1 has been shown to be correlated with poor outcomes, recurrence and drug resistance in various cancers." (PMID 28145098, 2017). "Recently, the Wee1 inhibitor AZD1775 was identified as a potential agent for targeting mutant KRAS-expressing cancers." (PMID 28978051, 2017). "To uncover molecular mechanisms behind replication catastrophe and to identify promising drug combinations for cancer treatment, we designed a flow cytometry-based screen combining different compounds with the Wee1 inhibitor MK1775." (PMID 28030798, 2017). "Several more recent studies have shown that Wee1 inhibition overcomes drug resistance in different cancers." (PMID 28145098, 2017). "Cancer cell growth was synergistically reduced both in vitro and in vivo by combined Wee1 and Chk1 inhibition, as compared to inhibition of each of these kinases alone." (PMID 28030798, 2017). "Among the top candidates include ATR, CHK1, WEE1 and several other genes, some of which are involved in DNA replication, cell cycle, DNA repair and cancer formation." (PMID 28262781, 2017). "In conclusion, a novel flow cytometry based compound screen revealed synergistic DNA damage in S-phase in cancer cells after simultaneous treatment with Wee1 and Chk1 inhibitors." (PMID 28030798, 2017). "To investigate the mechanism by which upregulated WEE1 protects CLMECs we considered ideas from cancer cell studies where AZD1775 has been found to induce double-stranded DNA breaks." (PMID 28178688, 2017). "As a control, we utilized a primary human keratinocytes; interestingly, IDH2 mRNA levels remained unchanged in these non-cancerous cells despite AZD1775 treatment, suggesting a cancer specific regulation of IDH2 by pY37-H2B/WEE1 signaling axis." (PMID 29290954, 2017). "Wee1 overexpression has been observed in several cancers, and high Wee1 expression has also been shown to correlate with tumor progression." (PMID 28978051, 2017). "A broad interest has developed among cancer researchers in the preclinical assessment of checkpoint inhibitors as cancer therapeutics, especially inhibitors of Chk1 and wee1." (PMID 27690219, 2016). "Previously, it has been reported that WEE1 is highly expressed in several cancers and has oncogenic roles." (PMID 27363019, 2016). "Of the rest, CPEB4, MCM4, RNF4, STAT2, and WEE1 were also shown to correlate with a number of cancer types." (PMID 27418131, 2016).
cancer (continued). "The cytotoxic effect can be explained by the addiction of hyper-replicating cancer cells to the ATR/Chk1/Wee1 signaling that protects them from replicative catastrophe." (PMID 26295265, 2015). "Pharmacological inhibition of the cell cycle regulatory kinase Wee1 represents a promising strategy to eliminate cancer cells." (PMID 26431163, 2015). "In our study, we found that Wee1 inhibition is particularly potent to eliminate gemcitabine-treated cancer cells, as compared to the inhibition of Chk1 or ATR." (PMID 25965828, 2015). "Such a use of Mdm2 inhibitors for avoiding the toxicities of cancer treatment is not limited to Wee1-inhibitors." (PMID 26431163, 2015). "Our results strongly suggest that Wee1 inhibition eliminates cancer cells not only by premature activation of chromosome separation but also by enhancing replicative stress through impairment of ATR/Chk1 signaling." (PMID 25965828, 2015). "The third strategy exploits genetically-determined defects in DNA repair pathways (mostly homologous recombination) that render cancer cells more sensitive to PARP or ATR/Chk1/Wee1 inhibitors." (PMID 26295265, 2015). "Inhibitors of the kinase Wee1 are capable of inducing cancer cell death with high efficiency, in particular when combined with chemotherapeutics such as nucleoside analogues or platinum compounds." (PMID 26431163, 2015). "These cancer cells are more sensitive to the partial inhibition of ATR/Chk1/Wee1 kinases compared to the healthy counterparts." (PMID 26295265, 2015). "The therapeutic efficacy of nucleoside analogues, e.g. gemcitabine, against cancer cells can be augmented by inhibitors of checkpoint kinases, including Wee1, ATR, and Chk1." (PMID 25965828, 2015). "Wee1 inhibition can be regarded as a way to exploit replicative stress for cancer treatment, as we have reviewed recently." (PMID 26431163, 2015). "PD407824 is a dual inhibitor of Chk1 and Wee1 and was shown to sensitize cancer cells to cisplatin and gemcitabine." (PMID 26295265, 2015). "We therefore propose that attenuated ATR/Chk1 represents at least one of the reasons why Wee1 inhibitors can synergize with a number of chemotherapeutics to trigger cancer cell death." (PMID 25965828, 2015). "Despite the attenuation of Chk1 by Wee1 inhibition, a number of studies still found cooperative effects when using inhibitors of Chk1 and Wee1 simultaneously for cancer treatment." (PMID 25965828, 2015). "Wee1 inhibitors represent promising anti-cancer drug candidates and are currently being tested in clinical trials of phases I and II (NCI Clinical Trials)." (PMID 25965828, 2015). "Targeted inhibition of WEE1 with AZD1775 has emerged as a strategy to sensitize cancer cells to cytarabine and other chemotherapeutics." (PMID 26334102, 2015). "A growing body of evidence indicates that targeting CHK1/CHK2 and WEE1 together can increase cytotoxicity in a variety of cancer cell types." (PMID 26025928, 2015). "As expected, all three inhibitors rendered cancer cells more sensitive to gemcitabine, but Wee1 inhibition proved to be particularly efficient in this context." (PMID 25965828, 2015). "In particular, the Wee1 inhibitor MK-1775 has been found efficient to eliminate a number of cancer cell species, and it is currently evaluated in numerous clinical trials (and 21 entries to clinicaltrial.gov)." (PMID 26431163, 2015).
cancer (continued). "Similar levels of excitement have been provoked by the success of a Wee1 inhibitor in pre-clinical models in which Wee1 inhibition promoted a lethal mitotic catastrophe in cancer cells whose DNA integrity was compromised." (PMID 24424027, 2014). "A decrease in the expression of the miR-16 family mediates resistance to cisplatin in cancer cells as a consequence of the increased levels of Wee1 and Chk1." (PMID 24796297, 2014). "To elucidate the roles of Wee1 in cancer cell cycle progression we have utilized siRNA knockdown and rescue." (PMID 24927813, 2014). "In SK-TRb cells, T3 down-regulated mRNA levels of Ccnd2, Cdk6, Cdc25, E2f3, c-Myb, Wee1 and Chk1 involved in cell proliferation and cancer." (PMID 24796297, 2014). "Inhibition of Wee1 in cancer cells resulted in the accumulation of DNA damage, alteration in cell cycle regulation with an arrest in the S-phase of the cell cycle, increased sub-G1 DNA content, and induction of apoptosis." (PMID 24223931, 2013). "Inhibition of Wee1 by MK1775 has been reported to enhance the cytotoxic effect of DNA damaging agents in different types of carcinomas." (PMID 23520471, 2013). "Knockout of WEE1 results in embryonic lethality before day 3.5, and knockdown of WEE1 is known to inhibit proliferation of several cancer cell lines in vitro." (PMID 23148684, 2012). "Previously published data suggested that over-expression of WEE1 is critical for the viability of some cancer types, and cell lines displaying higher levels of WEE1 expression are sensitive to WEE1 inhibition." (PMID 21358821, 2011). "Previous reports suggested that overexpression of WEE1 is critical for the viability of some cancer types, and cell lines displaying higher expression levels of WEE1 are sensitive to WEE1 inhibition." (PMID 21390271, 2011). "This indicates that WEE1 inhibition is a safe strategy to apply in OS patients because the radiosensitization would be cancer cell specific." (PMID 21529352, 2011). "Given that our RNAi data suggested that WEE1 is, in some contexts, critical for the viability of cancer cells that overexpress it, we investigated the role of this kinase further." (PMID 19357772, 2009). "Genome-wide gene expression in both cancer cells and skin tissues was analyzed to find a Wee1 gene signature that can be utilized in both tumor and surrogate tissues." (PMID 19500427, 2009). "Expression changes of the Wee1 inhibition gene signature in cancer cells have thus far been assessed only in cultured cell lines." (PMID 19500427, 2009). "Recent studies show that inhibition of key RS response kinases such as ATR, Chk1, or Wee1—which cancer cells depend on to survive under RS—can tip the balance toward mitotic catastrophe, especially when combined with genotoxic therapy or in tumors with high intrinsic RS." (PMID 41614897, 2026). "Consequently, investigating the mechanisms of WEE1 in these tumours and developing WEE1 inhibitors have become pivotal focuses of cancer therapy." (PMID 40859871, 2025). "Therefore, Wee1 has become an attractive target for cancer therapy, as its inhibition forces tumour cells with unrepaired DNA damage to death through the processes of replicative or mitotic catastrophe." (PMID 39528354, 2025). "Wee1 inhibition can synergistically enhance radiation and gemcitabine treatment in cancer." (PMID 41020877, 2025). "Therefore, Chk1 and Wee1 are considered promising therapeutic targets to enhance the effectiveness of radiotherapy in cancer cell killing." (PMID 39994186, 2025).